BTG1 (BTG anti-proliferation factor 1)
Diseases named in the same sentence as BTG1 in open-access papers (continued):
Sharing a sentence is not in itself a finding about the gene and the disease.
cancer (continued). "In addition, we will highlight the molecular mechanisms and biological consequences of BTG1 and BTG2 deregulation during cancer progression and elaborate on the potential clinical implications of these findings." (PMID 30350856, 2019). "Furthermore, there is evidence that expression levels of BTG1 and BTG2 can be used as prognostic biomarkers in various cancers." (PMID 30350856, 2019). "In this study, we also found that TOB1, BTG1 and BTG3 could be a prognostic marker or potential therapeutic target in several cancer types, consistent with previous reports." (PMID 28922388, 2017). "Univariate analysis using Kaplan-Meier method indicated that the cumulative survival rate of the cancer patients with weak, moderate, or strong expression of BTG1 was obviously lower than that without its expression (p < 0.05)." (PMID 26050197, 2015). "Forced BTG1 overexpression decreased the expression of PI3K, Akt, Bcl-xL, survivin, VEGF, and MMP-2 mRNA and protein; these are target factors in our cancer research, which have clear roles in the regulation of cellular apoptosis and proliferation, and thus were examined in this study." (PMID 24084718, 2013). "Additionally, Kaplan–Meier analysis showed the negative correlation between BTG1 mRNA expression and overall survival rate of all cancer patients (P < 0.05)." (PMID 33330092, 2020).
infection (2 papers, 2015 to 2022). The state of being infected such as from the introduction of a foreign agent such as serum, vaccine, antigenic substance or organism. "Pattern "Virulent" includes 14 genes whose expression levels were not changed after infection with heat-inactivated MTB H37Rv or the attenuated vaccine strain BCG (e.g. MAP3K4, SEMA4G, BTG1), and only one of these also belongs to the pattern "Virulent" at 18 hours post-infection." (PMID 26586179, 2015).
BTG1 also shares sentences with these, for which no sentence is quoted: B-cell precursor acute lymphoblastic leukemia (3 papers); metastasis (3); medulloblastoma (2); acute leukemia (1); adenocarcinoma (1); Allergy (1); B-cell chronic lymphocytic leukemia (1); benign tumors (1); cerebellar tumors (1); chronic myeloid leukemia (1); clear cell renal cell carcinoma (1); CNS lymphomas (1); diabetes (1); diabetic retinopathy (1); E. coli infection (1); follicular lymphoma (1); gastrointestinal disease (1); hematological malignancies (1); Hepatic steatosis (1); infectious disease (1); malignant brain tumors (1); Obesity (1); ovarian benign tumors (1); parasitemia (1); pulmonary fibrosis (1); sarcoma (1); scleroderma (1); signet ring cell carcinoma (1); squamous cell lung carcinoma (1); squamous cell skin carcinoma (1).
A further 1 disease shares a sentence with BTG1 in 1 paper.